MT-TF (mitochondrially encoded tRNA-Phe (UUU/C))
Synonyms: trnF; formerly MTTF
Gene: Mitochondrial transfer RNA gene on chromosome MT (577 to 647, forward strand). Ensembl gene ENSG00000210049.
Gene Ontology:
Molecular function: triplet codon-amino acid adaptor activity
Biological process: translation
Gene-disease validity (ClinGen):
ClinGen rates the evidence that MT-TF causes each of these diseases.
mitochondrial disease (mitochondrial): Definitive.
Diseases named in the same sentence as MT-TF in open-access papers:
MT-TF is named in the same sentence as 10 diseases in open-access papers, as found by Europe PMC text mining. Sharing a sentence is not in itself a finding about the gene and the disease.
MT-TF shares sentences with these, for which no sentence is quoted: dementia (1 paper); Encephalopathy (1); lactic acidosis (1); Leber hereditary optic neuropathy (1); MELAS (1); MERRF (1); mitochondrial encephalomyopathy (1); Myoclonic Epilepsy with (1); rhabdomyolysis (1); Stroke (1).